CD4 (CD4 molecule)
Diseases named in the same sentence as CD4 in open-access papers (continued):
Sharing a sentence is not in itself a finding about the gene and the disease.
leukemia (continued). "The percentage of this cell fraction among both CD4+ and CD8+ T cells is significantly higher in patients with leukemia relapse compared with patients in remission." (PMID 26230954, 2015). "Similar to p16p19−/−; Kras(G12V) histiocytic sarcomas and leukemias, MLL-AF9/DsRed tumors were CD48hi (95.8±2.4%), CD47hi (95.3±2.9%), Mac1hi (83.4±7.8%), Gr1mid/lo (20.2±2.4%), and B220−/lo, CD4−/lo, CD8−/lo, Ter119−/lo (n = 10)." (PMID 22952867, 2012). "The typical immunophenotype of T-LGL leukemia cells was CD45+bright, CD2+bright, CD3+bright, CD4-, CD8+bright, CD25-, and CD43+weaker." (PMID 18474096, 2008). "We found that NLM and mice presenting a polyclonal non-neoplastic CD4+/CD8+ population (pre-leukemia) presented a rather similar metabolic profile, which differed substantially from that seen in leukemic mice." (PMID 38928249, 2024). "After we successfully validated radiolabeling and specific in vitro binding of 89Zr-hCD4-Mb and 89Zr-mCD4-Mb to CD4+ cells, we examined the in vivo PET uptake of 89Zr-hCD4-Mb by HPB-ALL leukemia xenografts (which constitutively express the hCD4 antigen) subcutaneously (s.c.) implanted into NSG mice." (PMID 39239511, 2024). "Flow cytometric analysis demonstrated that leukemic mice treated with inhibitor showed a significant reduction in GFP + leukemic cells in the PB, which correlated with increased levels of CD4 + and CD8 + T-cells and a reduction in the levels of PMN-MDSC or leukemia induced neutrophils." (PMID 38730491, 2024). "Furthermore, in HIs and patients with leukemia in DN/RR states, CD103+CD8+ T cells were more prevalent than CD103+CD4+ T cells within the same peripheral blood sample." (PMID 39391310, 2024). "Thus, the highest-avidity TCR, S117A-TCR should be the most promising TCR for developing CD4+ T cell-based adoptive T cell therapy against HLA class II-positive WT1-expressing malignancies, such as leukemia." (PMID 36939853, 2023). "Among T-cell subsets, CD8+ cytotoxic T cells (CTL) were significantly expanded in Sig15 KO recipients, making the proportion of CD8:CD4 T cells comparable with levels in mice without leukemia." (PMID 37465593, 2023). "The spleen is a secondary lymphoid organ rich in immune cells involved in hybrid resistance.There was a significantly greater number of host CD4 T cells and CD8 T cells expressing PD-1 in spleens of F1 mice receiving HVEM WT leukemia cells than those receiving HVEM KO leukemia cells." (PMID 37033927, 2023). "Thus, the AML mice generate leukemia antigens that induce an immunosuppressive microenvironment that supports CD8+ and CD4+ T cell exhaustion." (PMID 36681742, 2023). "The crucial role of CD4 CAR T cells was recently pointed out by Melenhorst and colleagues, who observed that CD4+ CAR T cells dominated the CAR T cell population of patients with decade-long leukemia remission at later monitoring time points." (PMID 37799719, 2023). "Therefore, we compared Aicda expression in sorted Irf4−/− and wt fr.A-D cells to that of wt mesenteric (m)LN- and CD4+ TH1-cells as controls and to individual leukemia samples." (PMID 35459909, 2022). "Given that clinical manifestations of SS are sometimes mild, it can be presumed that pSS is not diagnosed in some patients with CD4+ T-LGL leukemia." (PMID 36362126, 2022). "CD4+ CAR-T cells have shown great promise in leukemia patients, where CD4+-, not CD8+ CAR- T cell treatment led to long-term tumor eradication." (PMID 35099641, 2022). "As expected, leukemias expressed T-cell specific markers (Lck, CD4, CD8, and TCRα and β), but not B-cell specific genes (e.g. Pax5, CD79a or IgM), indicating they were of T-cell origin." (PMID 35581375, 2022). "As a CD4+ T-cell malignancy, ATCL cells frequently exhibit complicated aneuploidy, including trisomy 3/7, sectional excision of 6q, and anomalies of 14q11, in contrast to cells from all other leukemias." (PMID 36497125, 2022).
leukemia (continued). "In the AML_GSE116256 dataset, FLT3LG is mainly expressed in CD4+ T cells, but compared with the PBMC_30K_10× dataset, the expression level of FLT3LG is remarkably reduced, and FLT3 is mainly expressed in leukemia cells and precursor cells." (PMID 36081495, 2022). "In this study, we constructed a novel LEX-based vaccine by combining CD4+ T cells with costimulatory molecules gene-modified LEXs, which harbor upregulated CD80 and CD86, and the anti-leukemia immunity of CD80 and CD86 gene-modified LEX-targeted CD4+ T cells was investigated." (PMID 36466863, 2022). "It was shown that CD4-specific chimeric antigen receptor (CAR)-engineered T cells (CD4CAR T cells), when in co-culture with CD4+ T cell leukemic cell lines (KARPAS 299 cells, primary leukemia cells from a patient), eliminated CD4+ T leukemic cells." (PMID 34368398, 2021). "When IRAK1 KO#7 cells were inoculated into the four different groups of mice, disease did not develop in isotype treated mice but leukemia developed in mice that were depleted either individually for CD4 or CD8 or combined CD4/CD8 cells." (PMID 34906138, 2021). "Further, Gzma–/– CD4+ T cell recipients exhibited no signs of GFP+ leukemia cells in the bone marrow upon euthanization, and the only cause of death was GVHD (17%)." (PMID 32809971, 2020). "In general, the BM contains a higher percentage of CD4+ T cells than PB, and whether this alteration is related to the AML microenvironment or if the CD8+ T cells are activated when migrating to the leukemia BM requires further investigation." (PMID 32082573, 2020). "Therefore, transferring IL-27 pre-stimulated polyclonal iTregs reduces systemic TNFα secretion, the expansion of cytokine secreting donor CD4 and CD8 T cells, and inflammatory cell infiltration in the colon, while preserving the graft-versus-leukemia activity." (PMID 32117306, 2020). "To test whether leukemia cells need to be killed for their miHAs to be cross-presented we transplanted B6 mice with CD45.2+ C3H.SW BM, Kb−/−H60+ BC-CML along with C3H.SW CD4 cells, which mediate GVL in this model." (PMID 32839441, 2020). "In 22/24 recipients injected with hCD45+ G+C+ cells (FACS sorted from day 24–25 N+ LTB-transduced CB cultures), we obtained G+C+ leukemias of T-cell lineage, typically CD7+ CD2+ sCD3+/− CD1a+/− and variable CD4/CD8 pattern including CD4− CD8− (DN), CD4+ CD8+ (DP), and CD4− CD8dim (SP8dim)." (PMID 31266935, 2019). "Furthermore, these CD4CAR-redirected effector cells exhibited profound killing capacity against CD4-positive AML cells in vivo, and efficiently controlled leukemia progression and prolonged survival in xenograft mouse models." (PMID 31413761, 2019). "Finally, the role of CD4-positive T cells and their interaction with CD8-positive T cells remains to be demonstrated on leukemia stem cells." (PMID 28638379, 2017). "DC-loaded with DNR-treated AML cells were more efficient than DC-loaded with ARA-C-treated cells not only, as expected, in inducing leukemia-reactive CD8+ T cells, but also in increasing the frequency of CD4+CD25+Foxp3+ T cells (11.70 ± 4.15 versus 5.97 ± 3.10%, respectively; p < 0.05)." (PMID 29312358, 2017). "This occurred in both CD4+ and CD8+ T cells from leukemia relapse patients." (PMID 26230954, 2015). "More importantly, co-transfer of isolated CD4+CD25+ Tregs with CD4+CD25− conventional T cells into an MHC-mismatched mouse with leukemia were able to prevent GvHD but did not prevent the GvT response." (PMID 24605111, 2014). "In general, both CD4 and CD8 T-cell subsets contribute to graft-versus-leukemia (GvL) reactions." (PMID 25415267, 2014). "There are 3 possibilities that could explain the suboptimal concordance between the frequency of CD4+CD25-CD69+ T cells and leukemia relapse." (PMID 24984576, 2014). "AML patients with IDO-positive blasts were shown to have a higher frequency of circulating bona fide CD4+CD25+ Treg cells compared with patients harboring IDO-nonexpressing leukemia blasts." (PMID 24903009, 2014).
leukemia (continued). "This is in contrast to the shared clonotypes as seen in CD4+/TCRαβ+ and TCRγδ+ T-LGL leukemia and might point to a more random clonal selection in TCRαβ+ T-LGL leukemia." (PMID 24413066, 2014). "The results from the clinical analysis suggested that these non-traditional CD4+CD25–CD69+ Tregs were correlated with leukemia relapse after allo-HSCT." (PMID 24984576, 2014). "Since the PD-1+ CD4+ T cell population increases markedly in aged and leukemic animals, it is therefore likely to contribute to the compromised TCR-response in development of cancer and thus to influence the development of leukemia." (PMID 24404186, 2014). "However, pretreatment with chidamide but not decitabine significantly inhibited the proliferation of both CD4+ and CD8+ T cells activated by anti-CD3 and anti-CD28 mAbs, suggesting a possible inhibition of anti-leukemia T cell immunity by chidamide in vivo." (PMID 23940586, 2013). "Human CD4+ Jurkat cells are commonly used in screening anti-HIV-1 drugs, but other reports have indicated dandelion root extract shows a selective induction of apoptosis through the activation of caspase-8 in human leukemia cells (Jurkat)." (PMID 22078030, 2011). "The slightly elevated Foxp3 expression in the CD4+CD25− population of ATL patients may reflect the presence of leukemia cells." (PMID 19654865, 2009). "In contrast, we see no binding with cervical carcinoma, several human leukemias, CD4 and CD14 subpopulations nor with human neutrophils." (PMID 16504122, 2006). "Translationally, pre-infusion CD3+ T-cell counts and CD4+/CD8+ ratios offered actionable thresholds for patient stratification, while achievement of minimal residual disease negativity by day 28 emerged as a critical early indicator of long-term leukemia-free survival." (PMID 41181124, 2025). "Unexpectedly, the nearby naïve CD4 T cells and DCs had significantly higher expression of TNFRSF12A, which codes for the corresponding receptor TWEAKR (also known as FN14 and CD266) than that of the same cell types at least 30 μm away from the closest leukemia cell." (PMID 40632867, 2025). "Surprisingly, the nearby naïve CD4 T cells and DCs had significantly higher expression of TNFRSF12A, which codes for the corresponding receptor TWEAKR (also known as FN14, CD266) than that of the same cell types at least 30 microns away from the closest leukemia cell." (PMID 39975227, 2025). "Moreover, type I interferon (IFN) produced by putative DCs could enhance CD8+ T cell-mediated GVHD and graft-versus-leukemia (GVL), although protecting recipients from CD4+-mediated GVHD." (PMID 39328417, 2024). "In addition, we detected increased expression of PD-L1 on the NFKBIE-ko leukemia cells as well as increased expression of PD-1, TIGIT and LAG3 on CD4+ and CD8+ T-cells from the spleens of mice with NFKBIE-ko tumors, consistent with the exhausted phenotype predicted by the RNAseq analysis." (PMID 38486128, 2024). "In this setting, neither CD4.28z or CD4.BBz CAR-T cells were able to counteract leukemia growth." (PMID 36593069, 2023). "If CLL cells were finally eradicated back in 2010, in the long phase the CD4+ cells destroyed only the natural B-cells and it could be argued that their “anti-leukemic properties” were studied with no leukemia cells." (PMID 37970204, 2023). "We developed a novel, oral, helper epitope-containing WT1 protein vaccine (B. longum 2656) to examine whether or not B. longum 420/2656 combination further accelerates the CD4+ T cell help-enhanced antitumor activity in a model of murine leukemia." (PMID 36803483, 2023). "Indeed, in a recent study in leukemia patients that developed long time tumour remission after CAR therapy, the responsible CAR T cell population was formed almost completely of persisting cytotoxic CD4+ T cells." (PMID 37122720, 2023).
leukemia (continued). "The high levels of CD4+ T cells producing IL-10 were described in asymptomatic carriers as a possible immunoregulatory mechanism that guarantees their asymptomatic clinical status, and IL-10 blockage in ATLL patients collaborates with leukemia-initiating cell eradication." (PMID 37711742, 2023). "The objective of the present study was to examine whether or not B. longum 420/2656 combination further accelerates the CD4+ T cell help-enhanced antitumor activity in a model of murine leukemia." (PMID 36803483, 2023). "In fact, a high-avidity TCR, S117A-TCR-transduced CD4+ T cells had a higher frequency of granzyme B/perforin-double positive cells and showed more potent cytotoxicity against WT1-expressing and HLA-DPB1*05:01-positive leukemia cells, compared to wt-TCR-transduced CD4+ T cells." (PMID 36939853, 2023). "In a preliminary study, our data showed that, unlike DEX, LEXs-targeted CD4+ T cells could not induce an efficiently anti-leukemia immune response." (PMID 36466863, 2022). "Interestingly, CD4+ T cells controlled leukemia progression, as indicated by lower spleen weight and leukemia cell content per spleen compared to mice without T-cell transfer." (PMID 33526861, 2021). "Knocking out SIRT1 did not change the CD4+ CD8+ phenotype of leukemia cells." (PMID 34407842, 2021). "Similar to the leukemia that develops in NRAS(G12D) only mice, recipient mice that received ΔβCat-TCF7-SPI1 only had an enlarged thymus, limited splenic invasion, and a more mature CD4+/CD8+ immunophenotype with similar disease latency (median DFS = 67.5 days)." (PMID 34230493, 2021). "This study confirms our previous results showing that a timely recovery of CD4 T cells (>50 CD4+ T cells/μL at two consecutive measurements within 100 days post-HCT) is the strongest predictor of leukemia-free survival, non-relapse mortality, as well as overall survival." (PMID 32974239, 2020). "HLA-DPB1*05:01-WT1332-TCR-modified-CD4+ T cells displayed a strong proliferative response and Th1-type cytokine production in response to WT1332 peptide, WT1 protein, or WT1-expressing tumor cell lysate and lysed HLA-DPB1*05:01+ WT1+ human leukemia cells via the granzyme B/perforin pathway." (PMID 30622438, 2019). "Indeed, 5-Aza-dC treatment has previously shown to induce PD-L1 demethylation and consequential mRNA and/or protein re-expression in the KG1 leukemia cell line, in vitro activated primary CD8+ T cells, CD4+ and CD8+ T cells from patients with myelodysplastic syndrome and acute myeloid leukemia." (PMID 29088766, 2017). "Contributions of CD4+ T cell in leukemia are not well defined." (PMID 28629373, 2017). "Therefore, we sought to assess the clinical correlation between the number of CD4+CD25-CD69+ T cells in donor bone marrow and leukemia relapse after allo-HSCT, and we also performed a preliminary exploration into the potential immune mechanism responsible for this association." (PMID 24984576, 2014). "Our study indicates that the antileukemic activity of lenalidomide is not due to the direct cytotoxicity against leukemia cells, but rather it may imply indirect mechanisms through the activation of nonmalignant immune cells, particularly NK and CD4 T cells." (PMID 25313353, 2014). "Endogenous CD4+ T cells, however, might be dysfunctional in vivo, as they have a normal intrinsic cytokine-producing ability only in vitro, but not in the leukemia environment." (PMID 24427158, 2013). "However, our findings contrast with those in a model of leukemia, in which CD4+, but not CD8+, T cells were required and the findings in a fibrosarcoma model, where both T cell subsets were necessary." (PMID 20849618, 2010). "Therefore, usage of CD4+ T cells directed against DM-sensitive antigens might allow induction of graft-versus-leukemia effect without GvHD." (PMID 34266882, 2021). "Therefore, donor CD4 T-cells after allogeneic stem cell transplantation (alloSCT) may mediate graft-vs.-leukemia reactivity without graft-vs.-host disease (GVHD)." (PMID 30619360, 2018).
leukemia (continued). "Of note, while only CD4– and not CD4+ iNKT cells expressed NKG2D at baseline, upon exposure to leukemia cells, both fractions displayed expression of NKG2D to nearly 100%." (PMID 40898981, 2026). "Moreover, the upregulation of IL-10 secretion by CD4+CD25+ICOS+ Tregs indicated that the expansion of Tregs in AML could be achieved through the ICOS/ICOSL pathway, which enhances the body’s immunosuppressive ability and induces leukemia cells to immune escape and drug resistance." (PMID 40008144, 2025). "HSTL typically features CD4/CD8 negative T-cells expressing the γ/δ T-cell receptor subtype, whereas T-LGL leukemia is usually characterized by CD8+ T-cells with α/β T-cell receptor." (PMID 37920595, 2023). "In summary, this study presents the first clinical evidence for the positive correlation between non-traditional CD4+CD25-CD69+ Tregs and leukemia relapse after allo-HSCT, although further study is necessary to confirm our findings." (PMID 24984576, 2014). "We next compared the frequency of CD4+CD25-CD69+ T cells between groups of patients with (n = 14) and without leukemia relapse or relapse indication (n = 42) at each time point after transplantation." (PMID 24984576, 2014). "Importantly, three weeks of DT injections of control (without leukemia) DEREG mice lead to a minor activation of T cells, mostly CD4+ T cell subpopulation." (PMID 35296093, 2022). "Thus in our analysis we have compared purified CD4; CD8 negative thymocytes from wild type (healthy) mice with those from a leukemia pre-disposition model and corroborated with a panel of human T-ALL samples." (PMID 30962539, 2019). "Interestingly, high Blimp-1 expression in CD4+, not CD8+ T cells, correlates with high circulating leukemia blast, suggesting a potential unique contribution of CD4+ T cell dysfunction in AML pathogenesis." (PMID 28629373, 2017). "This study provides the first clinical evidence of a correlation between non-traditional CD4+CD25-CD69+ Tregs and leukemia relapse after allo-HSCT and suggests that exploration of new methods of adoptive immunotherapy may be beneficial." (PMID 24984576, 2014). "However, we demonstrated that CD25 expression did not correlate with Ki-67 expression, suggesting that CD25+ cells do not favor leukemia cell proliferation, probably because CD25 is expressed not only by Tregs but also by activated conventional CD4+ and CD8+ T cells." (PMID 36901957, 2023). "In addition, Nfkb1-deficient leukemic cells presented a cell surface marker phenotype (expression of variable levels of CD4, CD8, CD24, CD25, and TCRβ/CD3ε) similar to that of Nfkb1-proficient cells (data not shown) and characteristic of transgenic TEL-JAK2 leukemia." (PMID 18596915, 2008).